MIR4664 (microRNA 4664)
Synonyms: hsa-mir-4664
Gene: MicroRNA gene on chromosome 8 (143,733,083 to 143,733,153, reverse strand). Ensembl gene ENSG00000265660.
Homologues: Orthologues: chimpanzee MIR4664 (100% identical).